LANCL1 (LanC like glutathione S-transferase 1)
Diseases named in the same sentence as LANCL1 in open-access papers:
LANCL1 is named in the same sentence as 22 diseases in open-access papers, as found by Europe PMC text mining. Sharing a sentence is not in itself a finding about the gene and the disease. The quoted sentences say what the papers report.
prostate carcinoma (6 papers, 2018 to 2024). A carcinoma that arises from epithelial cells of the prostate gland. "LanCL1, a peptide‐modifying enzyme component in eukaryotic cells, serves as a glutathione transferase and is reportedly associated with breast cancer and prostate cancer." (PMID 36321566, 2023). "Here we describe Lanthionine synthase C-like protein 1 (LanCL1), a member of the LanCL family, is a potential prostate cancer susceptibility gene." (PMID 29416001, 2018). "Furthermore, LanCL1, as a potential prostate cancer (PCa) susceptibility gene, can also protect PCa cells from oxidative stress and promotes cell proliferation." (PMID 33117306, 2020). "Although we showed the important role of LanCL1 in prostate cancer progression, the underlying mechanism is still largely unknown." (PMID 29416001, 2018). "In consideration of the important role of ROS in CRPC development and chemotherapeutic drugs resistance, there is an urgent need for further study of digging out other function of LanCL1 in prostate cancer." (PMID 29416001, 2018). "All these results suggest that LanCL1 protects prostate cancer cells from H2O2-induced cell death mainly through suppressing JNK signaling activity." (PMID 29416001, 2018). "The expression of LanCL1 is significantly higher in prostate cancer tissues compared with benign prostatic epithelia." (PMID 29416001, 2018). "To further confirm LanCL1 protein expression levels in prostate cancer progression, we examined expression of LanCL1 by IHC in prostate cancer tissues." (PMID 29416001, 2018). "To investigate the role of LanCL1 in prostate cancer, we first investigated the expression of LanCL1 in different tissues." (PMID 29416001, 2018). "To test the biological relevance of LanCL1 in prostate cancer cells, we examined the effect of LanCL1 overexpression and knocking down on cellular phenotypes." (PMID 29416001, 2018). "As what happens in neuron cells, LanCL1 also protects prostate cancer cells from high-level ROS, nevertheless, the mechanism is not the same." (PMID 29416001, 2018). "After excluding the possibility that LanCL1 protects prostate cancer cells through mitigating oxidative stress, we wonder how LanCL1 makes it." (PMID 29416001, 2018). "We found that LanCL1 promotes prostate cancer cell proliferation and protects cells from oxidative damage." (PMID 29416001, 2018). "LanCL1 promotes prostate cancer cell proliferation and helps protect cells from damage caused by oxidative stress." (PMID 29416001, 2018). "To further research the function and mechanism, in the study, we overexpressed or knocked down LanCL1 in prostate cancer cells and found that LanCL1 promotes cell proliferation by influencing cell cycle." (PMID 29416001, 2018). "Previous studies have shown us that LanCL1 involves in cellular process related to ROS and oxidative stress, thus making us interest in its role in prostate cancer." (PMID 29416001, 2018). "Clinical data also indicate that LanCL1 upregulation in human prostate cancers correlates with tumor progression." (PMID 29416001, 2018). "LANCL1 was reported to protect prostate cancer cells from oxidative stress." (PMID 39712016, 2024). "Additionally, glutathione S-transferase LANCL1 is involved in oxidative stress response and is overexpressed in prostate cancer cells." (PMID 35629968, 2022). "To examine whether LanCL1 plays the same role in prostate cancer cells, we cultured wild-type prostate cancer cells LanCL1 overexpression or knockdown cells." (PMID 29416001, 2018). "All these results revealed that LanCL1 expression level correlates with advanced tumor stage and poor prognosis in prostate cancer patients, suggesting that LanCL1 is likely involved in the tumorigenesis and progression of prostate cancer." (PMID 29416001, 2018). "Therefore, we will investigate the mechanism how LanCL1 inhibits JNK pathway activity in prostate cancer in the following study." (PMID 29416001, 2018).
prostate carcinoma (continued). "We observed increased expression of LanCL1 during prostate cancer development." (PMID 29416001, 2018). "Results showed that LanCL1 promotes prostate cancer proliferation." (PMID 29416001, 2018). "The expression of pSAPK/JNK (Thr183/ Try185) was found to be high in the low LanCL1-expressing prostate cancer cell line LNCaP, whereas the expression was low in high LanCL1-expressing PC-3 and DU145 cells, indicating the inverse correlation between LanCL1 and p-JNK expression levels." (PMID 29416001, 2018). "In summary, we found upregulated LanCL1 expression in prostate cancer tissues." (PMID 29416001, 2018). "Importantly, immunostaining for LanCL1 was significantly stronger in more aggressive prostate cancer tissues, as indicated by Gleason score." (PMID 29416001, 2018). "Furthermore, immunohistochemical analysis of prostate tissue sections for LanCL1 in WT and TRAMP mice at 25 weeks of age showed that LanCL1 expression level was upregulated in the TRAMP prostate cancer tissues." (PMID 29416001, 2018). "Taken together, these findings indicated that LanCL1 could protect prostate cancer cells from high-level H2O2-induced cell death." (PMID 29416001, 2018). "Similarly, the more aggressive prostate cancer cell lines express higher level of LanCL1." (PMID 29416001, 2018). "All these results indicate that LanCL1 may serve as an oncogene in prostate cancer." (PMID 29416001, 2018). "Therefore, further study would clarify the biological significance of LanCL1 in prostate cancer." (PMID 29416001, 2018). "Data from The Broad-Novartis Cancer Cell Line Encyclopedia (CCLE) and The Human Protein Atlas portal showed that the expression of LanCL1 is higher in prostate cancer tissues and human prostate cancer cell lines, which suggests that LanCL1 may be upregulated in prostate cancer cells." (PMID 29416001, 2018). "To examine the connection between LanCL1 and p-JNK in prostate cancer, we determined LanCL1 and p-JNK expression in different prostate cancer cell lines." (PMID 29416001, 2018). "In this study, we demonstrated that LanCL1 highly expresses in prostate cancer tissues, TRAMP prostate cancer tissue, and especially in high-grade tumor tissues and metastatic prostate cancer cell lines." (PMID 29416001, 2018). "LanCL1 does not help mitigate ROS level in prostate cancer cell, but suppresses the pathways downstream of oxidative stress." (PMID 29416001, 2018). "Online data sets and immunohistochemical analysis of clinically localized prostate cancer cases demonstrated that prostate cancer cells were positive for LanCL1, whereas weak or no staining of LanCL1 was observed in non-tumor samples." (PMID 29416001, 2018). "By deeply querying online data sets, we found that LanCL1 expresses higher in tumor tissues, but found no reports that explain the role of LanCL1 in the initiation and progression of prostate cancer." (PMID 29416001, 2018). "Furthermore, LanCL1 does not contribute to the cell migration of prostate cancer cells and EMT progression." (PMID 29416001, 2018).
amyotrophic lateral sclerosis (4 papers, 2017 to 2024). Amyotrophic lateral sclerosis (ALS) is a neurodegenerative disease characterized by progressive muscular paralysis reflecting degeneration of motor neurons in the primary motor cortex, corticospinal tracts, brainstem and spinal cord. "LANCL1 expression was found to be increased at presymptomatic stages of amyotrophic lateral sclerosis (ALS), in the SOD1G93A transgenic mouse model, indicating a possibly significant role of LANC1 in this neurodegenerative disease." (PMID 39796447, 2024). "LanCL1 has been proven to protect neurons in amyotrophic lateral sclerosis (ALS) mice, while the gut microbiota can also ameliorate the symptoms of ALS mice." (PMID 33117306, 2020).
diabetes (2 papers, 2022 to 2026). "Our findings suggest that diabetes-overexpressed miR-10b disrupts redox balance by targeting GCLM and LANCL1, which potentially leads to increased oxidative stress and cellular vulnerability in diabetic corneas." (PMID 41115935, 2026). "The increased muscle expression of LANCL1 in LANCL2 KO mice, as compared with WT siblings, may explain why LANCL2 KO mice with STZ-induced diabetes respond to ABA similarly to, or perhaps even better than, WT mice." (PMID 35736456, 2022).
chronic prostatitis (1 paper, 2020). An infectious or non-infectious chronic inflammatory process that affects the prostate gland. "The roles that LanCL1 and the gut microbiota play in chronic prostatitis are worthy of further exploration." (PMID 33117306, 2020).
cognitive decline (1 paper, 2025). "For instance, in LANCL1, the sites altered during refolding and cognitive decline are more diffuse and are not as close to one another." (PMID 40644533, 2025).
epilepsy (1 paper, 2023). A brain disorder characterized by episodes of abnormally increased neuronal discharge resulting in transient episodes of sensory or motor neurological dysfunction, or psychic dysfunction. "The functions of Mvd, Lancl1, Aldh3b1 and Hsdl2 in epilepsy are still worthy to be explored in our future studies." (PMID 36894540, 2023).
hepatocellular carcinoma (1 paper, 2024). A malignant tumor that arises from hepatocytes. "A general, cell type-independent role of the LANCL1/2 receptor system in protecting cells against radicals also emerges from very recent reports on hepatocellular carcinoma cells and on testicular cells." (PMID 39335584, 2024). "Specifically, a consistent negative correlation was observed between LANCL1 expression and ROS levels, as well as ROS-responsive gene expression, in hepatocellular carcinoma (HCC) cell lines." (PMID 39335584, 2024).
Hyperglycemia (1 paper, 2022). An increased concentration of glucose in the blood. "LANCL2 KO mice spontaneously overexpress LANCL1 in the SkM (approx. twice the amount of their WT siblings), allowing us to test whether LANCL1 could mediate the beneficial effect of chronic ABA treatment on hyperglycemia induced by low-dose STZ." (PMID 35736456, 2022).
hyperhomocysteinemia (1 paper, 2017). A serious metabolic condition caused by mutations in the MTHFR gene, medications, or nutritional deficiency. "Therefore, it is possible to hypothesize that lanthionine may interfere with AdoMet binding by increasing the stability of the LanCL1-CBS complex, thus increasing the inhibitory function of LanCL1 on CBS, leading to hyperhomocysteinemia." (PMID 28075397, 2017).
male infertility (1 paper, 2022). The inability of the male to effect fertilization of an ovum after a specified period of unprotected intercourse. "It is suggested that the lanthionine synthetase components C (LanCL1) gene might be associated with male infertility." (PMID 36552898, 2022). "Additionally, The LanCL1 gene was said to be important in the process of oxidative stress, which was also one of the mechanisms of male infertility." (PMID 36552898, 2022). "Our study would elucidate the potential effects of the LanCL1 gene in various testicular cells, which might pave the way for the further mechanistic investigation of the LanCL1 gene in the male infertility on the single-cell level." (PMID 36552898, 2022). "Our study would be the first to discuss the functions of the LanCL1 gene in the various testicular cells and their interactions on the single-cell level, which might be beneficial to further research on the mechanisms of male infertility in single-cells." (PMID 36552898, 2022).
myocardial ischemia (1 paper, 2024). A disorder of cardiac function caused by insufficient blood flow to the muscle tissue of the heart. "Finally, the protein levels of xanthine oxidase (XO), which produces O2− after sulfhydryl oxidation as occurs during myocardial ischemia/reperfusion (I/R), were about 6-fold lower in LANCL1/2-overexpressing vs. double-silenced cells." (PMID 39335584, 2024).
Obesity (1 paper, 2024). Accumulation of substantial excess body fat. "A deficiency of hypothalamic LanCL1 aggravated obesity-induced metabolic dysfunctions and hypothalamic inflammation, while an overexpression of hypothalamic LanCL1 was protective against these defects." (PMID 38397850, 2024). "We found that neuronal-expressed LanCL1 in the hypothalamus was highly correlated with the progress of HFD-induced obesity." (PMID 38397850, 2024). "Considering the maintenance of hypothalamic redox balance implicated in systemic metabolic regulation, we wondered if disturbed antioxidant defense mediated by LanCL1 would affect the progress of obesity and its related metabolic disorders." (PMID 38397850, 2024). "Early before the onset of obesity, we found increased mRNA and protein levels of hypothalamic LanCL1 in mice with one-week supplement of HFD, while robust suppression of this was present in obese mice supplied with HFD for 14 weeks." (PMID 38397850, 2024). "Collectively, these data indicated an essential role of hypothalamic LanCL1 to maintain the glucose homeostasis and mitigate obesity progress induced by HFD." (PMID 38397850, 2024). "In addition to these, we noticed differences in the impairment of glucose homeostasis induced by obesity between LanCL1 Ctr and cKO mice, and the obese cKO mice had higher levels of blood glucose, insulin, and leptin than the obese Ctr mice." (PMID 38397850, 2024). "We hypothesized that this phenotype represented the process of hypothalamic antioxidant defense regulated by PGC-1α being overwhelmed by HFD exposure, which contributed to obesity, and LanCL1 may be a target of PGC-1α." (PMID 38397850, 2024). "Interestingly, during the progress of HFD-induced obesity, we noticed a fluctuant expression pattern of the antioxidant gene LanCL1 in the hypothalamus." (PMID 38397850, 2024). "The attenuated hypothalamic LanCL1 indicated an overwhelmed antioxidant defense during obesity progress, as we found accumulating redox imbalance in the hypothalamus, showed by levels of increased oxidized glutathione and decreased reduced glutathione, as well as a reduced ratio of NADPH and NADP." (PMID 38397850, 2024). "Here, in this study, with genetic mouse models targeting antioxidant gene LanCL1 in the hypothalamus, we evaluated the effects of altered hypothalamic antioxidant defense on HFD-induced obesity." (PMID 38397850, 2024). "All these results provided evidence showing PGC-1α was involved in the response of LanCL1 to HFD exposure, and suggested an important role of the PGC-1α–SP1–LanCL1 axis in protecting against HFD-induced obesity." (PMID 38397850, 2024). "Here, with mouse models targeting the antioxidant gene LanCL1 in the hypothalamus, we demonstrate that impaired hypothalamic antioxidant defense aggravates HFD-induced hypothalamic inflammation and obesity progress, and these could be improved in mice with elevated hypothalamic antioxidant defense." (PMID 38397850, 2024). "Furthermore, perturbed expression of hypothalamic LanCL1 affected the hypothalamic inflammatory response under HFD exposure, suggesting critical roles of redox homeostasis in regulating inflammation in the hypothalamus during the development and progress of obesity." (PMID 38397850, 2024). "All these results suggested that hypothalamic LanCL1 overexpression is protective, but not completely resistant, against HFD-induced obesity and disorders in metabolic homeostasis." (PMID 38397850, 2024).
prostate tumor (1 paper, 2018). "We next examined LanCL1 expression in 15 cases of prostate tumor and matched nontumor tissues by western blot." (PMID 29416001, 2018).
neurodegenerative disease (5 papers, 2010 to 2025). A disorder of the central nervous system characterized by gradual and progressive loss of neural tissue and neurologic function. "A decrease in the abundance of those two types of bacteria in LanCL1 KO mice further indicates that neurodegenerative disease and systematic dysfunction could result in the loss of probiotics in the gut." (PMID 33117306, 2020). "Recent studies suggested that the LanCL1 gene was an important glutathione binding protein expressed in the mammalian central nervous system, significant to neurodegenerative disease." (PMID 36552898, 2022). "These facts indicate that LanCL1 expression may be dysregulated in neurodegenerative diseases, such as ALS." (PMID 31570855, 2020). "Recent research has identified that LanCL1 is a glutathione binding protein, taking part in antioxidant activities and protecting neurons, which may have a role in neurodegenerative diseases." (PMID 33117306, 2020). "It has been suggested that LanCL1 might be significant for neurodegenerative diseases and in cellular signaling and differentiation." (PMID 20731849, 2010).
tumor (3 papers, 2018 to 2025). "The prostate cancer susceptibility gene LanCL1 can protect tumor cells from oxidative stress damage, ultimately leading to tumor progression." (PMID 39849606, 2025). "Furthermore, we also found the association between LanCL1 expression and Gleason score and tumor stage." (PMID 29416001, 2018). "Consistently, by successful construction of a xenograft tumor model of PC-3 cells, we confirm that upregulation of LanCL1 expression promotes the growth of tumor in vivo." (PMID 29416001, 2018). "We found that the upregulation of LanCL1 significantly correlate with higher Gleason score and more aggressive tumor stage." (PMID 29416001, 2018).
cancer (1 paper, 2018). A tumor composed of atypical neoplastic, often pleomorphic cells that invade other tissues. "LanCL1 enhances cancer cell proliferation, and protects cells from ROS via suppressing JNK signaling pathway, mainly." (PMID 29416001, 2018). "Suppression of LanCL1 by siRNA results in increased cancer cell apoptosis." (PMID 29416001, 2018). "Meanwhile, we confirmed that LanCL1 could stimulate cancer cell proliferation, making us deliberate whether it may contribute to cancer progression through some mechanisms other than ROS." (PMID 29416001, 2018). "There have been reports that verified the relationship between LanCL1 and cancer." (PMID 29416001, 2018). "LanCL1 does not mitigate oxidative level in cancer cells, but inhibits specific pathways, such as JNK pathway, in order to exert the protective role." (PMID 29416001, 2018).
LANCL1 also shares sentences with these, for which no sentence is quoted: Alzheimer disease (1 paper); Atrophy (1); brain disease (1); breast carcinoma (1); infection (1); metabolic disorders (1).